IFNG (interferon gamma)
Diseases named in the same sentence as IFNG in open-access papers (continued):
Sharing a sentence is not in itself a finding about the gene and the disease.
tumor (continued). "At the same time, attraction of the immune cells into the tumor environment is causing a high level of stimulatory cytokines (e.g., interferon-gamma)." (PMID 30577521, 2018). "We showed that even if T cells secreting GzmB, TNFa, and IFNg were more numerous the cytotoxicity produced by cNK populations against the tumor was higher in RBPJ-deficient mice, even after T cell transfer." (PMID 29930552, 2018). "As expected, in subcutaneous tumor models, macrophage TgMGLL largely potentiated mRNA levels of TNFα, IL-6, and IFNγ in tumor-associated CD8+ T cells, and this effect was prevented by additional macrophage TgCB2." (PMID 29968710, 2018). "The loss of IFNγ signaling limits immune cell recruitment and immune recognition of tumor cells by suppressing the production of IFNγ-dependent chemokines and diminishing antigen presentation." (PMID 29977240, 2018). "In human SCC, tumor infiltration of IL-17A-producing Vδ1+ and Vδ2+ T cells was associated with a negative prognosis, in contrast to a more favorable outcome associated with tumor-infiltrating IFNγ-producing γδ T cells." (PMID 30538697, 2018). "CTLA-4 blockade was associated with increased IFNγ-producing tumor-infiltrating T cells and extended survival of dexamethasone-treated mice." (PMID 29891009, 2018). "We found that the tumor-associated CD8+ T cells from the TgMGLL mice expressed notably higher level of IFNγ than the WT mice, indicating a dominate role of TgMGLL on CD8+ T cells, but not on CD4+ T cells." (PMID 29968710, 2018). "In another study, tumor-associated neutrophils stimulate T-cell proliferation and interferon gamma releases." (PMID 29983866, 2018). "TLR3 was selectively up-regulated by TC1 primary tumour cells and this was corroborated by enhanced expression of genes associated with the IFNγ signaling pathway." (PMID 29440650, 2018). "Mechanically, LNT decreased tumor vascular function by increasing IFNγ production and in a T cell-independent manner, which was associated with the accumulation of tumor-infiltrating myeloid cells." (PMID 30373628, 2018). "The exogenous delivery of the DC-derived cytokine IL-12 can recapitulate anti-tumour immunity associated with enhanced IFNγ signalling within the TME." (PMID 29157300, 2017). "Here, the authors show that immunoediting is associated with an increase in genomic rearrangements of tumour cells that requires both cytotoxic T cells and IFNγ exposure." (PMID 28233863, 2017). "It is therefore likely, that partially activated TATs are a major source of IFNγ within the tumor microenvironment and the malignancy-associated ascites." (PMID 28327095, 2017). "This study also revealed the association of PD-L1 expression and TILs with IFNγ expression, which a prior human tumor cell line study revealed as an inducer of PD-L1 expression." (PMID 29088901, 2017). "NK, NKT, and CD8+ cells have been associated with tumor rejection and IFNγ upregulation after stimulation." (PMID 29109732, 2017). "All of these alterations in addition to gene mutations would predispose to JAK1/JAK2 inactivation and IFNγ-resistance in tumours if put under selective pressure by the immune system." (PMID 28561041, 2017). "It was also associated with an induction of systemic anti-tumour immunity with an increase in tumour-specific IFNγ-producing CD8+ T-cells in the spleen and other lymphoid organs and ultimately was associated with a survival benefit in treated mice." (PMID 29157300, 2017). "Several markers have been reported to reflect the association of inflammation and tumor, such as interferon-gamma/interleukin-4 ratio and inflammation-based prognostic score based on CRP and albumin levels." (PMID 27125872, 2016). "The presence of IFNγ within the tumor microenvironment has been shown to be associated with improved clinical outcomes to both cancer vaccination and immune checkpoint inhibition." (PMID 26885372, 2016).
tumor (continued). "These set of data implicate that tumor antigen reactive T cells with higher capacity to produce IFNγ have a direct co-relation to increased susceptibility to cell death, and a majority of these cells undergo necroptotic death upon repeated TCR activation." (PMID 27750220, 2016). "The TCP-1/TNFα and TCP-1/IFNγ combined treatment group inhibited tumor growth by different mechanisms from targeted TNFα or IFNγ alone which is highly associated with antitumor immunity." (PMID 27342639, 2016). "Interferon gamma (IFNγ) is one of the common cytokines coordinating tumor immune response and the associated biological consequences." (PMID 27486476, 2016). "More importantly, combination therapy of TCP-1/TNFα and TCP-1/IFNγ synergistically suppressed tumor growth and alleviated systematic toxicity associated with untargeted therapy." (PMID 27342639, 2016). "For example, treatment of tumor associated macrophages with the Cox-2 inhibitor celecoxib reduced M2 polarization and enhanced production of IFNγ, contributing to an antitumor environment." (PMID 27738494, 2016). "With the loss of MDSCs, splenic CD4+IFNγ+ cells and CD8+IFNγ+ cells were accordingly increased accompanied by recovery of lysis against 4T1 tumor cells in curcumin-fed tumor bearers." (PMID 27405665, 2016). "Interferon gamma (IFNγ) is one of the central cytokines that coordinates tumor immune responses and the associated biological consequences." (PMID 27486476, 2016). "In the complete response (CR) cases, 999 overexpressed genes including at least 234 tumor-specific CTL-activation associated genes such as IFNG, PRF1, and GZMB, were found in post-treatment biopsy specimens." (PMID 26625258, 2015). "Stat1 has been identified as a hub gene in several tumor-associated transcriptional networks including a gene network within HeLa cells exposed to IFNγ." (PMID 25902940, 2015). "The data from this and our previous studies show that the expression of the studied APM genes in MHC class I-deficient tumours can be increased both by IFNγ and DNA methyltransferase inhibitors." (PMID 25071011, 2014). "The objective of this study was to uncover the association of DNA methylation with IFNγ-mediated upregulation of genes encoding the components of APM in MHC class I-deficient murine tumour cell lines." (PMID 25071011, 2014). "In a mouse model, we showed that this causes IFNγ secretion by NK cells, followed by major histocompatibility complex expression by tumor cells, hence better recognition by T cells." (PMID 25170840, 2014). "The growth and propensity to give rise to lung metastases of MC38 tumors is augmented in IL-17-deficient mice, which is associated with decreased IFNγ+ NK and IFNγ+ tumor-specific T cells in the tumor draining lymph nodes and at the tumor sites." (PMID 24454480, 2013). "The spontaneously arising T cells were tested in an interferon-gamma ELIspot assay against a number of different nine-mer HLA-A2-binding peptides representing tumor associated CTL epitopes; Survivin-95, CEA-571, Her-2/Neu-369 and Her-2/Neu-654." (PMID 23787039, 2013). "Tumor cell-associated IL-1α also potentiates antigen presentation by the malignant cells themselves, possibly through IFNγ-induced MHC class II expression, and also via cross-presentation by professional APCs." (PMID 23847618, 2013). "We obtained evidence that systemic administration of the PPI esomeprazole (12.5 mg/Kg) to tumor-bearing mice caused a rapid (within 60 min) increase in tumor pH, which associated with enhanced IFNγ production by TILs." (PMID 24062984, 2013). "The anti-tumor efficacy of MIP has been associated with the induction of IFNγ as well as a reduction in tumor-associated TReg cells in mice." (PMID 23593454, 2013). "Th1 cells are considered the primary T-helper cell subset involved in antitumor responses; they have been associated with anti-tumor responses in mouse models, achieved in part by their secretion of IFNγ." (PMID 26344346, 2013).
tumor (continued). "Other studies have also emphasized the effectiveness of membrane-associated cytokines expressed on engineered tumor cells (i.e., IFNγ, GM-CSF, M-CSF, TNFα, and IL-12) (74, –76)." (PMID 23847618, 2013). "Indoleamine-2,3-dioxygenase (IDO) is expressed in response to interferon γ (IFNγ) and has been linked to both antiviral functions and to the immune escape of tumor cells." (PMID 22924042, 2012). "In vivo, defective responsiveness to IFNγ is associated with more aggressive tumor behaviour, while IFNγ-responsive tumors have a better chance to be kept in check by the immune system." (PMID 22919516, 2012). "Another appealing function of IFNγ is its influence on tumor-associated macrophages, which are often immunosuppressive." (PMID 21674047, 2011). "IFNγ, an NFκB inducible gene found in chronic inflammation, causes inhibition of tumor angiogenesis and represses tumor growth." (PMID 21994759, 2011). "Our studies indicate that autophagy activation in tumor cells from the mice treated prophylactically with the TLR4/9 agonist complex is associated with the elevated levels of IFNγ expression and STAT1 phosphorylation." (PMID 21931823, 2011). "As a key Th1 cytokine, IFNγ can shift the tumor-associated macrophage population towards the M1 anti-cancer phenotype." (PMID 21674047, 2011). "First, the STAT1-dependent development of tumor clones with an increased propensity for lung colonization and resistance to IFNγ is associated with the development of resistance to Dox." (PMID 19503789, 2009). "Of note, CD56dim NK cells stimulated by tumor cells were both cytolytic and IFNγ-producing, suggesting an association between these two effector functions of the CD56dim NK population." (PMID 18596908, 2008). "The tumor immune microenvironment plays a central role in modulating ferroptosis susceptibility: CD8+ T cell-derived IFNγ downregulates system Xc- and upregulates ACSL4, while other immune cells such as Tregs, MDSCs, and macrophages further fine-tune ferroptosis through cytokine and redox signaling." (PMID 41607787, 2026). "Functional analyses revealed that high-risk tumors are characterized by a distinct immune-tumor uncoupling phenotype, in which interferon-gamma (IFNG)-associated inflammatory signaling is preserved but fails to translate into effective antitumor immune activity." (PMID 42196154, 2026). "A 10-protein IFNγ-associated signature derived from baseline serum profile achieved an AUC of 0.68 for predicting pathological response, comparable to a previously reported tumour-based IFNγ gene signature (AUC = 0.67)." (PMID 41291768, 2025). "Upon reaching a critical bacterial density, the circuit was activated to induce coordinated lysis, releasing interferon‐gamma (IFN‐γ) along with pathogen‐associated molecular patterns (PAMPs), thereby enhancing local antitumor immunity and suppressing tumor growth." (PMID 40878391, 2025). "Furthermore, improved tumor-specific antigen reactivity was associated with higher levels of interferon-gamma (IFN-γ) produced by T cells." (PMID 40361336, 2025). "Conversely, lower serum levels of IFNg in HCC patients are associated with advanced tumor stage and worse prognosis, so monitoring for increases in serum IFNg is a potential modality for determining cold to hot HCC conversion, but this needs to be validated for standard clinical use." (PMID 41012682, 2025). "Interestingly, we observed that Fusobacterium load was also associated with MSI-H status and elevated levels of IFNγ, both associated with a cytotoxic anti-tumor response." (PMID 40895532, 2025). "High intratumoral CD8+ T_EX signatures and IFNγ signaling were found to be associated with considerably poorer overall and relapse-free survival in premenopausal women in a study utilizing early-stage ER+ tumor cohorts." (PMID 41550427, 2025). "Finally, the metabolic reprogramming mechanism of Nano-IFNγ/Zole on tumor-associated macrophages (TAMs) was studied in detail." (PMID 39776793, 2025).
tumor (continued). "This, combined with previous pre-clinical data which showed enhancement of checkpoint blockade responses in pathway mutants, suggests that tumours with mutations in the IFNγ pathway are as efficiently controlled by the immune system as tumours that are sensitive to IFNγ." (PMID 39746898, 2025). "The use of IFNG may enhance chemotherapy's effects by increasing tumor‐associated antigen release from dying cells, thereby strengthening the immune response against tumors." (PMID 39945555, 2025). "Similarly, activated CD4+ T cells secrete IFNγ + EVs to enhance STING activation in tumor-associated macrophages, reprogramming them toward a pro-inflammatory phenotype and eventually amplifying the efficacy of STING-based cancer immunotherapies." (PMID 40400306, 2025). "Ex vivo IFNg Enzyme-Linked ImmunoSpot (ELISpot) testing the reactivity of PBMCs to autologous tumor showed a tendency of increased reactivity in some patients (101.03, 101.04, 101.06, 101.12, and 101.15) after TIL infusion, but no significant changes were detected." (PMID 40107242, 2025). "Indeed, computational modeling has indicated that besides contact‐dependent T‐cell cytotoxicity, inhibition of tumor cell proliferation caused by IFNγ plays a major role in the ability of T‐cells to arrest cancer progression." (PMID 40178291, 2025). "MakA may skew TAMs toward tumoricidal functions, possibly through IFNγ-mediated signaling, which can override the tumor-promoting effects typically associated with M2-like cells." (PMID 41326332, 2025). "Beyond direct recognition and killing, intravital imaging experiments have shown that CD8+ T cells can modulate the behavior of distant tumor cells through IFNγ, including the generation of antigen-loss variants, increased PD-L1 expression, and tumor growth suppression." (PMID 40995371, 2025). "Loss of IFNγ-sensitivity by tumours is thought to be a mechanism enabling evasion, but recent studies suggest that IFNγ-resistant tumours can be sensitised for immunotherapy, yet the underlying mechanism remains unclear." (PMID 39746898, 2025). "Conversely, in LRG, the risk score exhibited a stronger positive correlation with IFNG expression (ρ = 0.1984, P = 0.002146), indicating a potentially enhanced anti-tumor immune response despite a higher correlation with T cell exclusion (ρ = 0.3204, P < 0.0001)." (PMID 41050691, 2025). "Compared to Veh, RETA treatment significantly enriched the expression of genes associated with several Hallmark pathways such as TNFA signaling via NFκB, interferon gamma and alpha responses, and inflammatory response which are associated with enhanced anti-tumor immunity." (PMID 40094000, 2025). "Indeed, some tumor cells with deficient MHC class I expression rely on IFNγ pretreatment to restore effective antigen presentation." (PMID 41584608, 2025). "Furthermore, when co-cultured with B16 tumor cells, Nr2f6-deficient NK cells exhibited significantly enhanced IFNγ production in percentages and MFI." (PMID 39920136, 2025). "Importantly, analysis of transcriptomic datasets suggests that similar immune remodelling occurs in human tumours carrying mutations in the IFNγ pathway." (PMID 39746898, 2025). "In addition to CCL5/IFNG expression in the diagnostic tumor biopsy our study also discloses the potential role of serum CCL5 and CXCL9 as early biomarkers of response to neoadjuvant treatment with anti-HER2 antibodies." (PMID 38167224, 2024). "Interferon-gamma is closely associated with IDO1 expression in tumor treatment and prognosis." (PMID 38539263, 2024). "Together, this suggests the increased IFNγ response observed in vivo may be due to elevated infiltration of IFNγ producing cells in Dock2 deficient tumours." (PMID 39242821, 2024).
tumor (continued). "Activating monocyte/neutrophil TREM1 with the agonistic antibody PY159 (IgG1) enhances co-stimulatory molecule expression and IFNγ responses to support anti-tumour immunity, but TREM1 is also associated with poor prognosis and inflammation-related carcinogenesis." (PMID 38831013, 2024). "Additionally, IFNγ can induce the expression of Fas and caspase-8 genes in tumour cells, rendering them more susceptible to FasL treatment." (PMID 38698968, 2024). "Previous studies in solid tumors have demonstrated that prolonged interferon signaling allows tumors to acquire STAT1-related epigenomic/genomic changes contributing to the maintenance of resistance to immune checkpoint blockades, with a major contributor of IFNG being tumor-associated T cells." (PMID 38339304, 2024). "To test whether the tumor-associated IFNγ and TNFα can stimulate the production of G-CSF, we treated MSCs with the two cytokines." (PMID 38690266, 2024). "We have found MAP2K1 (MEK1) as a functional protein in regressor EVs that could activate tumour‐associated macrophages to initiate an interferonγ (IFNγ)‐dependent anti‐tumour immune response." (PMID 39330930, 2024). "The involvement of ILC1s and TNFα in tumour development is further demonstrated through the observation that skin precancerous papilloma-associated ILC1 populations have the greatest ratio of TNFα+ cells to IFNγ+ cells, resulting in net pro-tumoural effects." (PMID 38745765, 2024). "Intriguingly, MG1 tumors are closely associated with tumor immunity, as evidenced by increased macrophage infiltration, as well as the involvement of B cells, platelets, and cytokines such as IL-6 and interferon-gamma (IFN-γ), as illustrated by the detection of protein abundance." (PMID 38879686, 2024). "Moreover, a quantitative assessment of immune response by the IFNγ ELISpot assay using irradiated autologous tumor cells or tumor-associated antigen to stimulate PBMCs was performed." (PMID 39041242, 2024). "Cells in node 16 which are IFNγ producing CD56+ effector γδ T cells might possess cytotoxic activity classically associated with anti-tumor responses." (PMID 38851856, 2024). "Mechanistically, Yap deletion caused the upregulation of beta-lymphocyte-induced maturation protein 1 (BLIMP1), which is an inducer of terminal T-cell differentiation, and elevated the production of interferon gamma (IFNγ) and tumor necrosis factor alpha (TNFα) which cause anti-tumor effects." (PMID 38538573, 2024). "Besides the loss of antigens, IFNγ facilitates immune escape by driving expression of PD-L1 in tumor cells to hamper anti-tumor immune responses through PD-L1/PD-1 axis-mediated dysfunctional TILs." (PMID 38216787, 2024). "Infiltrating Vγ1 γδ T cells have previously been identified as a potential source of IFNγ in tumours suggesting this immune cell population may be partly mediating IFNγ signalling in Dock2 deficient tumours." (PMID 39242821, 2024). "This defective recognition of cancer cells together with the upregulation of IFNγ in DOCK-2 deficient T cells may result in tumour promotion via increased expression of IDO1." (PMID 39242821, 2024). "Thus, the responsiveness of Dock2 deficient and normal tumour organoids to IFNγ stimulation is broadly similar." (PMID 39242821, 2024). "In this regard, macrophages were reported to produce IFNγ, and since in OC, tumor-associated macrophages (TAMs) constitute over 50% of cells in the peritoneal tumor implants and the ascites, they likely represent another source of IFNγ." (PMID 39123403, 2024). "Despite the expression of these exhaustion markers, antigen-specific intratumoral CD8 T cells were able to secrete IFNγ, TNFα, and Granzyme B upon ex vivo restimulation, showing that they maintained their functionality, which was associated with tumor regression." (PMID 38893156, 2024). "Mutations in JAK1/2 lead to reduced PD-L1 expression on tumor cells due to impaired IFNγ signaling." (PMID 37620318, 2023).